CD24 (CD24 molecule)
Diseases named in the same sentence as CD24 in open-access papers (continued):
Sharing a sentence is not in itself a finding about the gene and the disease.
tumor (continued). "To further characterize the proliferation status of CD44-expressing tumor cells during and after HER2 inhibition, we analyzed Ki67 positivity within CD24+ and CD44+ subpopulations." (PMID 40430044, 2025). "All PDGCAs expressed markers of tumor epithelial and stem cells (EPCAM, CDH1, KRT18, CA9, CD24, CD133), stromal and extracellular matrix components (COL3A1, COL5A1, DCN, PDGFRA, and PDGFRB), and mesenchymal stem cells (CD73, CD105, CD90)." (PMID 40723172, 2025). "Based on marker gene expression, we classified tumor cells into immune-responsive, EMT-like/proliferative, and Cd24+ clusters." (PMID 41444249, 2025). "When combined with the CD24-targeted ADC, 015s produced even greater antitumour activity and achieved complete tumour regression." (PMID 40806691, 2025). "Within the tumor microenvironment, the combined upregulation of CD47 and CD24 likely amplifies “don’t eat me” signaling, thereby enhancing resistance to macrophage-mediated phagocytosis and facilitating immune evasion." (PMID 41303350, 2025). "We further present a visualization of gene expression dynamics for MYB, CD24, CDH11, and VIM along with the spatial pseudotime trajectory, highlighting the progressive transcriptional shifts asso1ciated with tumor progression and EMT56." (PMID 40950184, 2025). "All three tumor cell lines exhibited downregulation of MHC class I (H2-Kb) and expressing CD24, Notch1, and c-Myc, typical markers for T-ALLs." (PMID 40534857, 2025). "Next, we detected the interaction between CD24 and ST8SIA6 in 4T1 cells and BRCA tumor tissues using immunofluorescence co-localization." (PMID 39791710, 2024). "We firstly analyzed the correlation between the expression of TRIM71 and tumor stem cell markers in HCC and HB and found significant positive correlation between TRIM71 and CD133, CD24, EPCAM, and LGR5 in HCC and HB tumor samples." (PMID 39267787, 2024). "CD44 and CD24 are important and widely recognized BCSC surface markers which are found in many tumor types and are often used together or in combination with other putative markers to isolate stem cells from solid tumors." (PMID 39469631, 2024). "Here the authors show that CD24-positive MM cells increase after BCMA-CAR-T treatment in patients, and that dual-targeted BCMA/CD24 CAR-T cells can improve anti-tumor efficacy in MM preclinical models." (PMID 38242888, 2024). "The results showed that the co-localization of ST8SIA6 and CD24 occurred in 4T1 cells and BRCA tumor tissues." (PMID 39791710, 2024). "The results show no statistical difference in the degree of TAMs (CD11b, marker of TAMs), B cells (CD24, marker of B cells), as well as NK cells (CD56, marker of NK cells) in tumor infiltration between the Ex and Ex-post models." (PMID 38622609, 2024). "We observed an expression of CD24, CD44, and NANOG, indicating a highly potent capacity to rebuild the tumor mass." (PMID 39408826, 2024). "The high expression of tumor-related genes (EPCAM, CD24, CDH1, ELF3, KRT18, KRT19, KRT8, and MUC1) in groups 10 and 11 suggests that cells in these groups are tumor cells." (PMID 38693422, 2024). "Mechanistically, YAP regulates CD24 expression by interacting with TEAD and binding the CD24 promoter to initiate transcription, which facilitates tumor cells to escape from the attack of macrophages." (PMID 38168654, 2024). "Consequently, CD24 appears to have a significant impact on the invasion and metastasis of tumor cells by facilitating the translocation and activation of integrins, primarily through the activation of Src kinase and potential focal interactions between CD24 and integrins." (PMID 38881902, 2024).
tumor (continued). "Significant change of expression, reaching 10- to 58-fold change between uterine lesion compared to non-tumor counterpart, was observed in CAPN6, CD24, HMGA1, PLAG1, SNORA48, and SNORD10 (upregulation) and DKK3 and STK26 (downregulation)." (PMID 37466765, 2024). "When NF2 was inhibited and YAP was overexpressed in TNBC cells, CD24 and FSP1 were inhibited, resulting in enhanced ferroptosis and TAM phagocytosis, hindering TNBC tumor growth." (PMID 39796693, 2024). "The results revealed the colocalization of IL21-AS1 with CD24 and HIF-1α in the cytoplasm, and the signals were specifically increases in hypoxic tumour regions." (PMID 38702326, 2024). "However, despite consistent tumor formation detected in control cells in the murine host, no tumors could be established from the CD24 knockdown variant." (PMID 38214542, 2024). "Despite the differences not being statistically significant, we can observe that the mRNA expression of stemness markers CD24 and CD44 were decreased in tumor tissues treated with NVB (P = 0.0687; P = 0.0796)." (PMID 38575587, 2024). "A series of preclinical studies have demonstrated that the gene expression of CD24 and CD47 is beneficial to increase the anti-tumor phagocytosis of macrophages." (PMID 38787372, 2024). "CD24 has been identified as a ligand for NKG2D, and this interaction has been shown to promote tumor immune evasion by suppressing NKG2D-mediated immune responses." (PMID 38881902, 2024). "In clinical tumor tissues, protein expression of SPIB, PLK1, and CD24 was up-regulated, while protein expression of NTRK3 and EDA2R was down-regulated." (PMID 39596658, 2024). "CD24 and CD47 are two types of membrane proteins broadly expressed by tumor cells, which can bind to signal proteins on the surface of macrophages, trigger the “don’t eat me” signal, and inhibit macrophage phagocytosis, thus escaping anti-tumor immunity." (PMID 38787372, 2024). "Immunohistochemical staining of nude mouse subcutaneous tumor model of SOX2, CD44, CHI3L1, and CD24 in vivo shows the same result, and IHC staining of TAM markers CD68 had no obvious change." (PMID 39619148, 2024). "Others have identified Notch3 as responsible for maintenance of CD24+, ITGB4+ tumor-propagating cells in a Kras model highlighting the possibility that Notch activation is required for this phenotype across models." (PMID 37882674, 2023). "Breast tumor CSCs have an increased tumor initiation potential and express various cell surface markers (e.g., low levels of CD24 and high levels of CD44) compared to other tumor cells." (PMID 37372954, 2023). "To assess the CSC property within the tumor cells, we used flow cytometry to determine the CD44 and CD24 distribution in the primary orthotopic tumor (SQ mammary fat) and metastatic lung lesions." (PMID 37298091, 2023). "Cancer stem cells, characterized as CD44+/CD24-/low expression and high ALDH activity, possess tumor initiation capacity, unlimited self-renewal competence and the ability of differentiating into heterogeneous cells." (PMID 36594100, 2023). "In detail, compared to the saline group, CyOA NPs + L treatment reduced the proportion of CD133+ tumor cells by 24.5%, side population cells by 94.1%, and CD44+CD24− tumor cells by 30.3%." (PMID 37680304, 2023). "CD24 acts as a ligand for NKG2D, suppressing NKG2D-mediated immune responses and facilitating tumor immune evasion." (PMID 38313430, 2023). "CSCs (CD44+CD24+) and NSCCs (CD44−CD24−) were then inoculated into the abdomen of nude mice, and the tumor weight and volume were found to be increased in the presence of CSCs compared with NSCCs." (PMID 37005676, 2023).
tumor (continued). "Evidence has shown that the tumorsphere- and colony-forming ability of tumor cells is regulated by the stemness of tumor cells and the enhanced stemness of CSCs is often closely related to the abnormal expression of CD44, CD24, CD133, and Lgr5." (PMID 37005676, 2023). "We also verified the positive correlation between ID1 expression and SOX9 (p = 6.90e‐05, r = 0.20), EPCAM (p = 5.37e‐06, r = 0.23), CD24 (p = 1.82e‐07, r = 0.27), and CLDN4 (p = 6.04e‐05, r = 0.18) expression in HCC tumor tissue from TCGA datasets." (PMID 37085918, 2023). "The binding of CD24 to Siglec-10 on the surface of B cells inhibits BCR-regulated signal transduction and promotes tumor escape." (PMID 36882399, 2023). "In the process of immunotherapy, the tumor microenvironment can be remodeled by targeting elimination of CD79A+CD24-PANCK+-BCSCs subpopulation or reversing the exhaustion of CD8+ T-cell, so as to restore the anti-tumor effect of effector T-cell." (PMID 38066053, 2023). "Compared to the non-tumor tissues, the expression levels of CD276 in all subgroups and CD24 in SHH, Group 3, and Group 4 subgroups are significantly higher." (PMID 36825029, 2023). "These demonstrated that CD24, CD45RB, and CD44 had relatively strong changes across all tumor types, rendering them the preferred candidates for panel inclusion." (PMID 37600768, 2023). "After analyzing the number of tumor stem cell–like cells in tumor tissue, THC can reduce the number of cells (CD44+/CD24−)." (PMID 36707875, 2023). "CD24 blockade in squamous cell-bearing mice has also been confirmed to reduce TAM and tumor growth in hematological malignancy." (PMID 37894750, 2023). "Compared with CD24+ liver CSCs and CD133+ liver CSCs, CD24+CD133+ liver CSCs have a stronger tumor-initiating capacity." (PMID 37581938, 2023). "These were trained using the CD24+EpCAM+VIM+-positive cell counts for each field of view, separated into tumour body and stroma using our imaging segmentation pipeline." (PMID 37975646, 2023). "The percentages of BCSC as well as expression of their markers, such as CD44, CD24, ALDH1, and CD133, are tumor-subtype dependent." (PMID 37445860, 2023). "tumor and/or ascitic fluid of 16 patients were characterized for MSCs phenotype (CD73, CD90, CD105), CSCs markers (CD24, CD44, CD133), and hematopoietic stem and progenitor marker (CD34) and leukocyte common antigen (CD45)." (PMID 37958844, 2023). "One of the tumor cell populations, CD45−CD56−(EpCAM+FOLR1+CD24+), demonstrated high expression of the markers." (PMID 37894472, 2023). "2.The interaction between the immune checkpoint proteins CD24 and LGALS9 in tumor epithelial cells, SIGLEC10 in dendritic cells, SIGLEC10 and HAVCR2 in macrophages increased." (PMID 37671151, 2023). "We discuss our findings on the anti-tumor mechanism of IMM47, a humanized monoclonal antibody (mAb) targeting CD24, which inhibits CD24/Siglec-10 interaction via macrophage antigen presentation while increasing NK cell cytokine release." (PMID 37846296, 2023). "With special regard to a tumor stem cell-like phenotype (CD24low, CD44high) and the potential to metastasize (represented by a CD44+ phenotype), CD24 and CD44 were included in the analysis." (PMID 37174080, 2023). "Both Cd24 and Cd47 were detected in KGN cells, suggesting the Cd24 and Cd47 were expressed in tumor cells of human GCTs." (PMID 36823373, 2023). "Strikingly, when analyzing the immunophenotype of tumor cells within this cluster, an upward trend in the expression levels of CD19, CD34, CD24, CD20, nuTdT, cyMPO, and CD33 was recorded." (PMID 38250553, 2023). "By combining EpCAM as a tumour lineage and EMT CSC marker, Vimentin as a mesenchymal marker, and CD24 as a plastic EMT CSC marker, we aimed to identify tumour cells that have undergone EMT and disseminated into the surrounding stromal region." (PMID 37975646, 2023).
tumor (continued). "Malignant ascites-derived exosomes are found to contain various cargos, including L1CAM, CD24, ADAM10, Claudin-4, and EMMPRIN, crucial for tumour progression." (PMID 38201468, 2023). "Analyses of hot tumors have revealed that cDC1 (CD24+XCR1+ DCs in mice, CD141+ XCR1+ DCs in humans) tumor-infiltrating dendritic cells (TIDCs) recognize tumor-derived DNA in the cytoplasm via cGAS." (PMID 37046775, 2023). "The results of this study demonstrated that OAd-SIRPα-Fc, OAd-Siglec10-Fc and OAd-TIGIT-Fc were able to produce SIRPα-Fc, Siglec10-Fc and TIGIT-Fc, respectively, which effectively bound to CD47+, CD24+ and CD155+ tumor cells." (PMID 38016957, 2023). "In the immediate vaccine model, CD24-Fc or human IgG-Fc control was injected simultaneously with the whole cell vaccine plus anti-PD-L1/CTLA4 antibodies at day 7, 10 and 13 post tumor inoculation." (PMID 37346042, 2023). "Hypoxia-activated pathways in the tumor microenvironment, such as HIF, CD133, CD24, CD47, DLK1, and mixed lineage leukemia 1 (MLL1), are the most essential contributing vital factors to CSC generation and maintenance." (PMID 37492478, 2023). "Together, these results indicated that the LeptoM3 and BCB adhesion cells expressed higher stemness markers CD44, CD133, and EPCAM and lower CD24 and the overexpression of ICAM2 promoted sphere formation and tumor initiation." (PMID 37620448, 2023). "Among these five prognosis-related genes, we found that INHBA and CD24 were oncogenic genes, while GRAMD1C, NFKBIA and ACSS2 were tumour suppressor genes." (PMID 35999846, 2022). "Gene expression profiles of the high-risk group correlated positively with the upregulation of CSC markers, CD24, CD44, CD20, FOXM1, and EpCAM, and significant enrichment of other ESC signatures, indicating that these were tumor-promoting targets." (PMID 35814473, 2022). "FACS showed that there was a significant scavenging effect on tumor-infiltrated Tregs after anti-CD25 antibody injection in control (CTR) and CD24+MDSC-DCs groups, although the number of Tregs was low in CD24+MDSC-DCs-treated mice (Fig. 4Band4D)." (PMID 35707772, 2022). "In G3 patients, CgA, CD56, Ki-67, CD24, CD44 and laminin were highly expressed in tumour tissue relative to that in non-tumour tissue with the exception of CD24 for one patient." (PMID 36362433, 2022). "In terms of tumor ligand expression, compared with the Saline group, the protein levels of CD47, CD24, and PD-L1 in the CON group were significantly increased (P<0.05)." (PMID 36186906, 2022). "The expression of CD24 and INHBA was significantly high in tumour tissue (P = 0.0102 and P < 0.001)." (PMID 35999846, 2022). "Despite extremely high tumor heterogeneity, malignant cell markers such as MUC1, CEACAM5, S100A11, CD24, and TM4SF1 were relatively uniformly upregulated in cancer cells and had the potential to serve as targets for SBA diagnosis and treatment." (PMID 36104333, 2022). "In conclusion, the antitumor activity of CD24+MDSC-DCs was achieved by inhibiting the polarization of CD4+T cells toward Tregs, therefore reducing the proportion of Treg in tumor and changing the immunosuppression of TME." (PMID 35707772, 2022). "Immunohistochemistry microarray was used to further confirm that protein expression of CD24, MMP1, SDC1, and SPP1 was much higher in tumor sections than in Para cancerous tissues." (PMID 35037689, 2022). "CD24 and CD44 expression has been described in tumors before, and they are involved in tumor survival and growth." (PMID 35954154, 2022). "A possible positive effect of SIRT in CCA patients is supported by the assessment of CD24 and CD44 that can be expressed by tumor cells and play an important role in their adhesion, survival and growth." (PMID 35954154, 2022). "Tumors were divided in two groups according to median of ESA+CD24+CD44+ or CXCR4+CD133+ cell percentage [high stemness tumor (HST) > median, low stemness tumor (LST) ≤ median]." (PMID 36142575, 2022).
tumor (continued). "In summary, miR-150 induced different responses depending on the cell type in the levels of tumor-initiating factors CD133 and CD24." (PMID 37529006, 2022). "Tumor cells overexpress anti‐phagocytic ligands CD47, PD‐L1 MHC‐I, and CD24, and can interact with their corresponding receptors SIRPα, PD‐1, LILRB1, and Siglec‐10 on the macrophages and send “don't eat me” signals to evade phagocytic clearance by macrophages." (PMID 37323705, 2022). "For example, tumour cell CD47 and CD24 engage cognate receptors on TAMs, signal regulatory protein-α (SIRPα) and sialic acid-binding Ig-like lectin 10 (Siglec-10), respectively, to trigger signalling cascades which inhibit macrophage phagocytosis." (PMID 35020853, 2022). "Contrary to their methylation level in tumor tissues, these genes showed very low CpG methylated sites in CD133 (19.4–25.8%), CD147 (26.7%), and CD24 (5–25%) in the normal oral mucosal tissue samples." (PMID 36498950, 2022). "Within G2, Ki-67 was lower in Patient 2, and CD24, CDX2 and CD45 were higher in Patient 1 relative to those in the non-tumour tissue, in contrast to the other tissues." (PMID 36362433, 2022). "Other CSC markers stimulated by the Wnt/β‐catenin pathway include CD24, Prom1, CD44, and ALDH1, thereby enhancing tumor stemness." (PMID 36226253, 2022). "The cells in clusters 3, 4, 6, 7, 10, 15, 23, 25, 26, and 35 originated from tumor specimens and were highly expressed in ALB, KRT18, and CD24; therefore, they were labeled as malignant cells." (PMID 36605219, 2022). "The IHC results of tumor tissue indicated that pEGFR and pS6 were highly expressed in TSC2-depleted tumor tissue, and CD24 exhibited considerable positive expression." (PMID 36231025, 2022). "The markers that distinguished G3 tumours from the lower grades were higher levels of synaptophysin, CD56, Ki-67, CD24, CD44, β-catenin and E-cadherin." (PMID 36362433, 2022). "Compared to epithelial cells (CD44 high/CD24 high), mesenchymal cells from MMTV-WNT-1(CD44 high/CD24 low) mice were tumor-initiating cells with greater tumorsphere-forming and migration abilities." (PMID 35186923, 2022). "Differential analysis showed that proliferation and antigen presentation genes, such as STMN1 and HLA‐DRA, were slightly up‐regulated in tumour cells, whereas differentiation molecules, such as KRT13, HOPX and CD24, were highly expressed in normal cells." (PMID 35608199, 2022). "With the aim of the timely diagnosis of such a form of tumor escape, our approach includes the obligatory examination of CD45, CD38, CD34 and CD24 expression vs. side-scatter (SSC) to find any suspicious cell populations among all nucleated cells." (PMID 36358863, 2022). "Using fresh retinoblastoma tissue, the co-expression of EpCAM and three other putative tumor stem cell markers CD44, CD24 and ABCG2 was examined." (PMID 36132125, 2022). "The existence of CSCs has been demonstrated by the expression of several surface biomarkers previously identified and reported in CRC, including CD24, CD44, and CD133, which are commonly used to isolate CSCs from heterogeneous tumour cells." (PMID 36612229, 2022). "The paradigm of early metastasis is featured in a small proportion of primary tumor cells containing high CD44 and low CD24 stem cell-like features which carry the potential to leave the primary tumor early to metastasize at distant sites." (PMID 35736645, 2022). "To further characterize MDSC-DCs obtained from different origins and culture systems, we examined expression levels of several DC markers, such as CD24, CCR7, CD117, and CD135 on the MDSC-DCs in 4T1-tumor bearing mice." (PMID 35707772, 2022). "CD24, CD44, laminin, CD49, CDX2, CK6 and DAXX had lower expression in the tumour relative to that in the non-tumour tissue." (PMID 36362433, 2022).